Y_RNA (Y RNA )
Gene: Miscellaneous RNA gene on chromosome 1 (7,982,881 to 7,982,983, reverse strand). Ensembl gene ENSG00000200344.
Homologues: Orthologues: chimpanzee Y_RNA (100% identical), macaque Y_RNA (97% identical), guinea pig Y_RNA (81% identical). Paralogues in human: Y_RNA (86% identical), RNY1 (84% identical), Y_RNA (84% identical), Y_RNA (83% identical), RNY1P7 (83% identical), RNY1P11 (82% identical), Y_RNA (82% identical), Y_RNA (81% identical), RNY1P8 (80% identical), Y_RNA (80% identical), RNY1P2 (79% identical), Y_RNA (79% identical), and 93 more.